ENSG00000288721 (novel protein)
Gene: Protein-coding gene on chromosome 6 (41,793,314 to 41,921,139, reverse strand). Ensembl gene ENSG00000288721.
Genetic constraint (gnomAD): Missense variants: 225 observed, 287.27 expected, observed/expected ratio (o/e) 0.78, 90% interval 0.7 to 0.88. Synonymous variants: 105 observed, 111.16 expected, observed/expected ratio (o/e) 0.94, 90% interval 0.81 to 1.11.